MYB (MYB proto-oncogene, transcription factor)
Description:
Transcriptional activator; DNA-binding protein that specifically recognize the sequence 5'-YAAC[GT]G-3'. Plays an important role in the control of proliferation and differentiation of hematopoietic progenitor cells.
Synonyms: c-myb; Cmyb; c-myb_CDS; efg
Tractability: Small molecule: a high-quality ligand is known. PROTAC: UniProt records ubiquitination sites on it; ubiquitination databases record sites on it; a small molecule that binds it is known.
Target class: Transcription factor
Gene: Protein-coding gene on chromosome 6 (135,181,308 to 135,219,173, forward strand). Ensembl gene ENSG00000118513.
Subcellular location: Nucleus
Subcellular location (Human Protein Atlas): Nucleoplasm; Cytosol
Pathways (Reactome):
Developmental Biology: Specification of the neural plate border; Transcriptional regulation of granulopoiesis
Gene expression (Transcription): RUNX1 regulates transcription of genes involved in differentiation of HSCs
Hemostasis: Factors involved in megakaryocyte development and platelet production
Signal Transduction: Estrogen-dependent gene expression
Gene Ontology:
Molecular function: DNA-binding transcription activator activity, RNA polymerase II-specific; protein binding; RNA polymerase II cis-regulatory region sequence-specific DNA binding; DNA binding; DNA-binding transcription factor activity; WD40-repeat domain binding
Biological process: erythrocyte differentiation; negative regulation of DNA-templated transcription; negative regulation of hematopoietic progenitor cell differentiation; negative regulation of megakaryocyte differentiation; negative regulation of transcription by RNA polymerase II; positive regulation of DNA-templated transcription; positive regulation of miRNA transcription; positive regulation of transcription by RNA polymerase II; T-helper 2 cell differentiation; mitotic cell cycle; myeloid cell development; regulation of DNA-templated transcription; cellular response to hydrogen peroxide; cellular response to retinoic acid; positive regulation of collagen biosynthetic process; positive regulation of glial cell proliferation; positive regulation of hepatic stellate cell activation; positive regulation of hepatic stellate cell proliferation; positive regulation of neuron apoptotic process; positive regulation of smooth muscle cell proliferation; positive regulation of testosterone secretion; positive regulation of transforming growth factor beta production; response to hypoxia; response to ischemia; skeletal muscle cell proliferation
Cellular component: nucleoplasm; RNA polymerase II transcription regulator complex; nuclear matrix; nucleus; cytosol
Genetic constraint (gnomAD): Loss-of-function variants: 22 observed, 70.9 expected, observed/expected ratio (o/e) 0.31, 90% interval 0.22 to 0.44. The upper end of that interval is the gene's LOEUF score, 0.44, which puts it in group 1 of 6, group 1 being the genes least tolerant of losing a copy. Missense variants: 593 observed, 836.32 expected, observed/expected ratio (o/e) 0.71, 90% interval 0.66 to 0.76. Synonymous variants: 269 observed, 299.89 expected, observed/expected ratio (o/e) 0.9, 90% interval 0.81 to 0.99.
Cancer hallmarks: escaping immune response to cancer (suppresses); proliferative signalling; escaping programmed cell death (promotes); invasion and metastasis (promotes); change of cellular energetics (promotes); proliferative signalling (promotes); suppression of growth (promotes); angiogenesis; tumour promoting inflammation
Homologues: Orthologues: chimpanzee MYB (99% identical), macaque MYB (99% identical), dog MYB (93% identical), pig MYB (93% identical), rabbit MYB (90% identical), guinea pig MYB (88% identical), rat Myb (87% identical), mouse Myb (76% identical), tropical clawed frog myb (65% identical), zebrafish myb (50% identical). Paralogues in human: MYBL1 (45% identical), MYBL2 (35% identical), SNAPC4 (18% identical), CDC5L (17% identical), DMTF1 (14% identical), TTF1 (9% identical).
Diseases named in the same sentence as MYB in open-access papers:
MYB is named in the same sentence as 228 diseases in open-access papers, as found by Europe PMC text mining. Sharing a sentence is not in itself a finding about the gene and the disease. The quoted sentences say what the papers report.
leukemia (132 papers, 2010 to 2025). A malignant (clonal) hematologic disorder, involving hematopoietic stem cells and characterized by the presence of primitive or atypical myeloid or lymphoid cells in the bone marrow and the blood. "METTL14 causes the occurrence and development of leukemia by modifying MYB/MYC-targeted genes with m6A RNA, and m6A promotes the translation of c-MYC, BCL2, and PTEN in leukemia patients." (PMID 38970366, 2024). "This confirms that BPDCN MYB fusions can initiate leukemia in hematopoietic progenitor cells associated with their binding to cell cycle genes." (PMID 39499902, 2024). "This was demonstrated by utilizing mutant alleles of MYB or p300 that disrupt their interaction, preventing leukemia formation in mice." (PMID 38542205, 2024). "The MYB oncogene is an oncogenic driver in the majority of leukemias and encodes a master transcription factor with critical roles in cell proliferation, cell survival, and leukemic stem cell maintenance." (PMID 37077825, 2023). "Mutations in and the overexpression of MYB were first discovered in leukemia cells and were recently discovered in solid cancers." (PMID 35240026, 2022). "In a subset of pediatric (3.7%) and adult (5.5%) T-ALL the LMO2 gene contains intronic indels that result in de novo binding sites for the leukemia-associated transcription factors MYB, ETS1 or RUNX1 and thus dysregulated LMO2 expression." (PMID 35514954, 2022). "As increasing evidence has implicated MYB in human leukemia, we became interested in developing a screening tool that would allow us to identify compounds with MYB-inhibitory activity." (PMID 35408476, 2022). "Among others, MYB has also been implicated in leukemia through its role in the survival of pre-B-cell acute lymphoblastic leukemia (pre-B-ALL)." (PMID 35408829, 2022). "Both mutations and translocations of MYB have causal roles in various human malignancies, including leukemias." (PMID 33527899, 2021). "MYB plays vital roles in regulating proliferation and differentiation of hematopoietic progenitor cells, dysregulation of MYB has been implicated in the pathogenesis of leukemia." (PMID 33637692, 2021). "Here, we showed the association of the −34k and −88k regions of MYB and the MYB promoter in human leukemia cells using circularized chromosome conformation capture (4C) assay." (PMID 33637692, 2021). "Increased expression of MYB in colon cancer, breast cancer, and leukemias was associated with cell proliferation, metastasis, and invasion." (PMID 34299042, 2021). "The deregulation or overexpression of c-MYB has been detected in a wide variety of human cancers and is associated with poorly differentiated tumors, including leukemia, colon and breast tumors." (PMID 30781655, 2019). "The transcription factor MYB plays key roles in hematopoietic cells and has been implicated the development of leukemia." (PMID 30177851, 2018). "The first mechanism is evident in leukemia samples, in which enhanced alternative RNA splicing produces variant MYB gene transcripts." (PMID 25279451, 2014). "Thus, understanding the underlying mechanisms of MYB-mediated drug resistance is of great significance for the treatment of leukemia." (PMID 40725394, 2025). "Besides leukemia, overexpression of MYB has also been implicated in the development of other malignancies, such as breast, colon and prostate cancer, adenoid cystic carcinoma (ACC) and low-grade glioma." (PMID 35408476, 2022). "Similarly, peptidomimetics that achieved the inhibition of the assembly of the c-MYB-CBP/P300 complex also caused leukemia cell growth arrest and extended survival of immunodeficient mice engrafted with MLL-rearranged leukemia cells." (PMID 34594227, 2021). "In leukemia samples, enhanced alternative RNA splicing produces mutated MYB gene transcripts." (PMID 34876130, 2021).
leukemia (continued). "MLL fusion proteins negatively regulated miR-150 production, and forced expression of miR-150 inhibited leukemic cell growth and delayed MLL-fusion-mediated leukemogenesis likely by targeting MYB, suggesting a miR-150-regulated MYB signaling underlying the pathogenesis of leukemia." (PMID 31164492, 2019). "MYB, the homolog of the avian myeloblastosis viral oncogene, functions in normal hematopoiesis, and deregulated MYB expression has been linked with human leukemia." (PMID 28212443, 2017). "MYB is proto-oncogene that has been identified to cause a range of leukemia." (PMID 24205155, 2013). "Thus MYB may mediate the associations of segment 17 with 141 leukemia-specific genes on other chromosomes." (PMID 20925909, 2010). "Aberrant MYB expression plays a critical role in the onset and progression of various hematologic malignancies, particularly leukemia." (PMID 40725394, 2025). "We overexpressed and knockdown MYB in human leukemia K562 cells and evaluated changes in ferroptosis-related markers, as well as cell proliferation and migration capacities, in the context of treatment with the chemotherapeutic agent sorafenib." (PMID 40725394, 2025). "This element was previously identified as a highly conserved enhancer (“MYB-enh-3”) in erythroid leukemia cells that shows correlation between MYB expression and chromatin accessibility in human blood cells." (PMID 41129262, 2025). "In summary, MYB plays a critical role in regulating chemoresistance through multiple mechanisms in various cancers, particularly in leukemia." (PMID 40725394, 2025). "Abnormal expression of MYB is closely related to leukemia progression, poor prognosis, and anticancer drug resistance." (PMID 40725394, 2025). "MYB is a transcription regulator crucial for hematopoietic regulation and is classified as an oncogene due to its link to leukemia and lymphoma." (PMID 40672391, 2025). "In this study, we found that MYB can inhibit sorafenib induced ferroptosis in human leukemia K562 cells through upregulating FTH1, conferring sorafenib resistance to leukemia cells." (PMID 40725394, 2025). "Despite these well-documented roles, the precise molecular mechanisms by which MYB contributes to chemotherapy resistance in leukemia remain largely undefined." (PMID 40725394, 2025). "Here, we showed that MYB inhibits sorafenib-induced ferroptosis in human leukemia, desensitizing these cells to sorafenib." (PMID 40725394, 2025). "Rescue experiments confirmed that FTH1 is required for MYB induced sorafenib resistance and ferroptosis inhibition in human leukemia cells." (PMID 40725394, 2025). "It echoes the critical associations of these two biomarkers with leukemogenesis: the MYB proto-oncogene contributes to the survival of leukemia stem cells, while AHSP is essential for erythroid differentiation." (PMID 40868100, 2025). "It is well known that MYB is highly expressed in various leukemia cells, which often leads to drug resistance." (PMID 40725394, 2025). "As in case of Celastrol, Plumbagin inhibited the proliferation of patient-derived AML to a stronger extent than the proliferation of normal hematopoietic progenitors, which is in line with the MYB addiction of the leukemia cells." (PMID 38542205, 2024). "Further cancers sensitive to MYB-targeted therapy include various leukemias (e.g., BCR/ABL-positive CML and ALL) and lymphomas (DLBCL, Burkitt lymphoma), gynecological cancers (ER-positive breast cancer, OC), gastrointestinal cancers, and CRPC." (PMID 38835346, 2024). "Since both compounds are in late clinical stage development or have already been approved for other diseases, it will be interesting to see if they can be repurposed for T-ALL and other MYB-driven leukemias." (PMID 38542205, 2024). "MYB was highly sensitive to sustained histone acetylation by the natural HDAC inhibitor trichostatin A (TSA) in leukemia cells." (PMID 38835346, 2024).
leukemia (continued). "The growth rate of MYB-expressing genotypes in this coculture system correlated with their leukemia-inducing potential in vivo." (PMID 39499902, 2024). "We first treated Cdkn2a-KO MYB::PLEKHO1 leukemia cells harvested from mouse spleens with ATRA in vitro." (PMID 39499902, 2024). "We found that our BPDCN MYB fusion–induced mouse leukemias showed sensitivity to ATRA in vitro and in vivo, while CAL1 human BPDCN cells displayed differentiation, cell cycle arrest, and apoptosis upon ATRA treatment in vitro." (PMID 39499902, 2024). "These alterations, including duplications and translocations, led to increased MYB expression in leukemia cells." (PMID 38542205, 2024). "MYB promoted leukemia stem cell phenotype via interaction with the insulin-like growth factor 2 mRNA-binding protein 1 (IGF2BP1), and IGF2BP1 knockdown sensitized leukemia cells to the DNA-targeting drugs doxorubicin, cyclophosphamide, and cytarabine." (PMID 38835346, 2024). "Our findings confirm that, in a mouse model, expression of MYB::PLEKHO1 is sufficient to initiate leukemia in hematopoietic progenitor cells." (PMID 39499902, 2024). "Recent research has further supported MYB’s active role in leukemia development, demonstrating that genomic alterations can lead to the formation of de novo MYB binding sites in the vicinity of other oncogenes, stimulating their expression." (PMID 38542205, 2024). "To further characterize BPDCN MYB fusion–induced leukemias, we first performed transcriptomic analysis using RNA-Seq." (PMID 39499902, 2024). "ATRA treatment caused loss of MYB in CAL1, as well as in BPDCN PDX samples, which also showed reduced leukemia burden in recipient mice after ATRA treatment in vivo." (PMID 39499902, 2024). "MYB overexpression was observed in leukemia, gastrointestinal cancers (colorectal cancer and pancreatic cancer), and breast cancer." (PMID 38835346, 2024). "Substantial strides have been taken in unraveling the pivotal role of MYB in human leukemia and various cancers." (PMID 38542205, 2024). "In KMT2Ar leukemias, c-MYB is essential for sustaining the leukemic phenotype by driving transcriptional programs that support the self-renewal and proliferation of leukemic cells." (PMID 39682203, 2024). "In vivo ATRA treatment in secondary recipients of Cdkn2a-WT MYB::PLEKHO1 or Cdkn2a-KO MYB::PLEKHO1 leukemias resulted in a significant reduction in disease burden." (PMID 39499902, 2024). "We performed RNA-Seq and CUT&RUN for V5 in Hoxb8-FL.MS5 cells to determine how MYB fusions initiate leukemia in these cells." (PMID 39499902, 2024). "An active role for MYB in leukemia development was suggested by the discovery of the recurrent chromosomal alterations of the MYB gene in T-cell acute lymphoblastic leukemia (T-ALL)." (PMID 38542205, 2024). "MYB fusions associated with BPDCN regulate cell cycling and promote myeloid-dendritic leukemia in vivo." (PMID 39499902, 2024). "The proliferation of MYC-expressing HL-60 leukemia and MYB-expressing CRC cells (LoVo, doxorubicin-resistant LoVo/Dx, and COLO-205) was inhibited by ODNs." (PMID 38835346, 2024). "In leukemia, mebendazole modulates MYB degradation by interfering with the heat shock protein 70 and exhibit the ability of impairing acute myeloid leukemia (AML) growth in vivo involving SP70/HSC70 chaperone pathway." (PMID 36994664, 2023). "Here, we sought to assess in more detail how the leukaemia phenotype-related dependence on MYB translates to human leukaemia that are driven by different genetic lesions." (PMID 37996430, 2023). "In the present study, we used siRNA-mediated MYB silencing and transcriptome profiling to explore the oncogenic addiction to MYB levels of human leukaemia driven by different genetic lesions." (PMID 37996430, 2023). "MYB is generally considered a proto-oncogene and it is often activated or overexpressed in cancer, including leukemia, colon, and breast cancer." (PMID 37478172, 2023).
leukemia (continued). "Previous studies have reported the capacity of MYB to influence leukaemia establishment and maintenance through enforcing a self-renewal program while suppressing myeloid commitment." (PMID 37996430, 2023). "Natural blockers of MYB overexpression have demonstrated promising results in leukemia; however, in ACC patients, preclinical investigation is difficult due to the lack of cell lines and in vivo models." (PMID 37476370, 2023). "Here, we investigate the role of MYB in human leukaemia by performing siRNA-mediated knock-down in cell line models of AML with different driver lesions." (PMID 37996430, 2023). "In this regard, we found that overexpressed MYB correlates positively with SENP1 expression in leukemia, breast, and colorectal cancer patients according to mining of data from TCGA." (PMID 37468105, 2023). "In AML, MYB rearrangements are rare; however, AML cells are often addicted to higher levels of MYB expression than normal hematopoietic progenitor cells, making the leukemia cells more vulnerable to MYB inhibition than their normal counterparts." (PMID 35408476, 2022). "Other studies showed that PBX1, HOXA, and MEIS1 bind to the MYB gene, activating and dysregulating it in leukemia." (PMID 35743243, 2022). "For example, the methyltransferase METTL-14 promotes the occurrence and development of leukemia via m6A RNA modification of MYB/myc." (PMID 37529797, 2022). "In myeloid leukemia, MYB is required to maintain the viability of the leukemia cells and to prevent their differentiation." (PMID 35406726, 2022). "c-MYB ablation results from disrupted HSP/HSC70 chaperone protein homeostasis in leukemia cells following induction of proteotoxicity and the unfolded protein response by WFA." (PMID 35368048, 2022). "MYBs are conserved across all eukaryotic species, and a conserved MYB in leukemia called cMYB has been considered a promising target for therapy." (PMID 35566279, 2022). "Recent work has demonstrated that MYB is involved in the development of human leukemia, especially in acute T-cell leukemia (T-ALL) and acute myeloid leukemia (AML)." (PMID 35408476, 2022). "Taken together, these lines of evidence make it likely that inhibitors of the MYB and C/EBPβ transcription factors would have an interesting potential as leads or drugs against leukemia and, possibly, other MYB- or C/EBPβ-dependent tumors." (PMID 35408476, 2022). "MiR-150 is considered to buffer MYB expression to a small range for sufficient MYB protein expression for B-cell development while preventing excessive expression leading to dysregulated expansion and leukemia." (PMID 35966635, 2022). "Recent investigations into the role of MYB in human leukemia have pin-pointed MYB as a potential drug target for AML and have stimulated research in the use of low-molecular-weight compounds as potential MYB inhibitors." (PMID 35406726, 2022). "Although no plant NF-κB equivalent has been found, other proteins that are critical to the maintenance of both plant and leukemia cells, such as the MYB proteins, have been identified." (PMID 35566279, 2022). "We provided further evidence that the introduction of MIR29B into KU812 leukemia cells significantly reduced MYB protein expression." (PMID 36507536, 2022). "For example, celastrol, a natural compound that targets the interaction of c-MYB with the transcriptional co-activators CBP/P300 has shown promising anti-leukemia activity in AML." (PMID 34594227, 2021). "Recent progress in understanding its role in leukemia has made MYB a promising target for drug development." (PMID 33958723, 2021). "A dramatic difference in the abundance of long-range contacts along chromosome 6 was observed between leukemia cells and HeLa cells, much more MYB related intra-chromosomal interactions were detected in leukemia cells than in HeLa cells." (PMID 33637692, 2021).